CCL2 (C-C motif chemokine ligand 2)
Diseases named in the same sentence as CCL2 in open-access papers (continued):
Sharing a sentence is not in itself a finding about the gene and the disease.
atherosclerosis (continued). "Hematopoietic ablation of Il27ra accelerated atherosclerosis due to enhanced activation of CD4+ T cells, in particular, Th17 cells, accompanied by increased IL-17A, TNF-α and IL-6 production, CCL2 chemokine expression and accumulation of myeloid cells." (PMID 28536468, 2017). "In atherosclerosis, CCL2 (also named MCP-1) is involved in initial steps of inflammation by attracting monocytes, T-cells and dendritic cells." (PMID 25978399, 2015). "Lastly, radiolabeled CCL2/MCP-1 (a chemoattractant for monocytes) was used to visualize sterile inflammation in rats, and atherosclerosis in rabbits." (PMID 25525560, 2014). "In cardiovascular disease in particular, there is evidence that multiple CC-CK and their receptors act in concert to promote atherosclerosis, since CCR2−/−, CCR5−/− and CCL2−/− mice have all shown reduced atherosclerosis in hyperlipidemic models." (PMID 25077938, 2014). "The significance of chemokines (CCL2 [monocyte chemotactic protein-1], CCL5 [RANTES] and CX3CL1 [fractalkine]) and their receptors (CCR2, CCR5 and CX3CR1) in atherosclerosis has been demonstrated in animal models and clinical studies." (PMID 22815945, 2012). "CCL2/CCR2B are involved in wide range of pathologies including multiple sclerosis, rheumatoid arthritis, atherosclerosis, cancer, and HIV-1 pathogenesis." (PMID 22870205, 2012). "The most elaborately studied chemokines in atherosclerosis, CCL2/MCP-1 and CCL5/RANTES, have been implied to reflect the burden of atherosclerotic lesions in cardiovascular disease patients." (PMID 23029252, 2012). "Monocyte chemoattractant protein-1 (MCP-1), a CC chemokine (CCL2), promotes atherosclerosis by recruiting macrophages and monocytes to the vessel wall." (PMID 22428064, 2012). "Taken together, these studies strongly suggest a direct role for CCL2 and CCR2 in monocyte recruitment and in the pathology of atherosclerosis." (PMID 20181074, 2010). "Further evidence for the role of CCL2 and its receptor CCR2 in the pathology of atherosclerosis has come from gene knock-out experiments in mice." (PMID 20181074, 2010). "Several lines of evidence support a role for CCL2 (monocyte chemotactic protein-1) and its receptor CCR2 in the development of atherosclerosis." (PMID 20181074, 2010). "Correspondingly, interventions targeting monocyte recruitment by disrupting MCP-1/CCL2 (monocyte chemoattractant protein 1) and CCR2 signaling have shown promise in mitigating excessive inflammation and conferring protection in mouse models of myocardial infarction and atherosclerosis." (PMID 40257974, 2025). "In the present study, we observed that patients with CAS had significantly elevated serum levels of CX3CL1, CXCL12, CCL19, CCL21, CCL2, and CCL5 compared to control individuals, suggesting that these chemokines are intricately involved in the initiation and progression of atherosclerosis." (PMID 40236901, 2025). "The role of MCP-1/CCL2 and sCD40L in atherosclerosis is well-established." (PMID 38338843, 2024). "Taken together, these results suggest that FDT may inhibit atherosclerosis by targeting SELP and CCL2." (PMID 38794213, 2024). "Through a combination of UFLC-TOF-MS, network pharmacology, and experimental validation, we found that FDT attenuated atherosclerosis and exerted anti-inflammatory effects by suppressing SELP and CCL2 gene expression, contributing to monocyte adhesion and migration." (PMID 38794213, 2024). "Conditional deletion of Ccl2 in SMCs does not inhibit the development of atherosclerosis in mice with PCSK9-induced hypercholesterolemia." (PMID 38234375, 2024). "Mest, Adipoq, Ccl2, and Pcsk9 emerged in the differentially expressed genes of the liver and plasma of PM2.5 model mice, which might mediate atherosclerosis accelerated by PM2.5." (PMID 37888673, 2023). "CCL2 signals through its receptor CCR2, which is required for monocyte emigration from the bone marrow during an inflammatory response, and deletion of CCR2 significantly reduces atherosclerosis." (PMID 37200978, 2023).
atherosclerosis (continued). "In our research, EPA lowered monocyte chemotactic protein-1 (MCP-1)/chemokine (C-C motif) ligand 2 (CCL-2) levels in serum, which means that EPA could attenuate inflammatory responses during atherosclerosis." (PMID 35464772, 2022). "The authors determined that, prior to atherosclerosis, the aortic tissue isolated from suPARTg mice secreted higher levels of C-C motif chemokine ligand 2 (CCL2) (also known as monocyte chemoattractant protein-1 [MCP-1]) and exhibited higher numbers of monocytes." (PMID 36519539, 2022). "Investigations of IL-33 in atherosclerosis revealed that this cytokine stimulates the expression of the endothelial adhesion molecules VCAM1, ICAM1 and E-selectin as well as the expression of CCL2 in HUVECs in a concentration-dependent manner resulting in increased leukocyte adhesion." (PMID 35600479, 2022). "The activations of CX3CR1 and CCR5 chemokine receptors, the CCR2-CCL2 axis stimulation or the overexpression of CCL2, CCL3, CCL4, CCL5, CXCL1 or CX3CL1 on endothelial cells have been reported to contribute to atherosclerosis development via neutrophil recruitment." (PMID 34440753, 2021). "It has been reported that in atherosclerosis, 7a-Hydroxycholesterol can elicit TLR6-mediated expression of IL-23 by monocytic cells via PI3K/Akt and MAPKs pathways, leading to inflammation via the upregulation of CCL2 and MMP-9 in macrophages." (PMID 34552973, 2021). "Additionally, enhanced cytokine expression (TNF, MCP-1/CCL2, IL6) and ROS production have been observed in monocytes from atherosclerosis patients." (PMID 34790973, 2021). "Assessment of circulating chemokines found that there were no significant changes in either CCL2 or CCL5 in the plasma for either model of atherosclerosis progression with M3." (PMID 28282403, 2017). "Our study establishes a link between CCL2, HDL, and endothelial cholesterol efflux and provides the first experimental evidence for the p42/44 MAPK-dependent mechanism of atherosclerosis mediated by CCL2 at the molecular and cellular levels using primary ECs relevant to atherosclerotic plaques." (PMID 27458015, 2016). "This suggests that circulating CCL2 levels are not increased by arsenic in this model of atherosclerosis." (PMID 26332580, 2015). "Indeed, the combined inhibition of both CCL2 and CCL5 activity led to additive inhibition of atherosclerosis." (PMID 25077938, 2014). "Interestingly, in these latter cells, NOV induces CCL-2 and CCL-5 (unpublished data), which are involved in the immune-inflammatory response of atherosclerosis." (PMID 23785511, 2013). "Monocyte chemoattractant protein 1 (MCP-1/CCL2) is a cytokine that attracts blood monocytes and tissue macrophages and is therefore involved in chronic inflammatory disorders, for example, atherosclerosis." (PMID 20652055, 2010). "Using MCP1/Ccl2 receptor-deficient mice to examine atherosclerosis, it was demonstrated that, in the absence of the receptor for MCP1/Ccl2, CCR2, there was a substantial reduction in arterial lipid deposition and diminished numbers of macrophages in the arterial wall." (PMID 40753563, 2025). "The chemokines CCL2 (also known as MCP-1 (monocyte chemoattractant protein-1)), CCL5, and CXCL10 (also known as IP-10 (interferon gamma-induced protein 10)) play a central role in the initiation and progression of atherosclerosis by recruiting and activating inflammatory cells." (PMID 40943241, 2025). "Therefore, the PG modulation of the CCL2/CCR2 pathway may be a safe and useful therapeutic strategy for the prevention of atherosclerosis." (PMID 39125901, 2024). "Since the combined blockade reduced atherosclerosis within the carotid artery, the site in which the fat transplant was located, our results suggest that the combined blockade of TNFα, CXCL2 and CCL2 reduced the ability of aged visceral fat to enhance atherosclerosis, at least locally." (PMID 36683460, 2023).
atherosclerosis (continued). "IL6, CXCL8, CCL2, SOD2, NFKBIA, and BIRC3 were identified as the top 6 hub genes in the magenta module (human cardiomyocyte samples) and were mainly enriched in the NOD-like receptor signaling pathway, IL-17 signaling pathway, TNF signaling pathway, lipid and atherosclerosis signaling pathway." (PMID 36426222, 2022). "Moreover, ICAM-1 and Ccl2 mRNA expression was elevated in the HFCD-induced atherosclerosis CON group compared with the NOM group, while the mRNA expression of those in the HFCD-induced atherosclerosis with GPE treated group decreased significantly (p < 0.05)." (PMID 36145277, 2022). "Therefore, CCL2 and CCL4 are novel therapeutic targets for regulating atherosclerosis." (PMID 35509837, 2022). "MCP-1, also known as CCL2 and mainly utilizing CCR2 as its receptor, is a representative of the chemokine CC family (β subfamily) which can help chemotaxis monocytes and plays a key role in atherosclerosis, ischemia–reperfusion injury of the heart, heart failure and other cardiovascular diseases." (PMID 36195874, 2022). "In our study, we mainly demonstrated that YB1 dephosphorylation attenuated atherosclerosis in vivo, and YB1 dephosphorylation decreased CCLs (CCL2, CCL7, CCL11, CCL12) expressions in VSMCs in vitro, which may be a critical determinant of the reduction in atherosclerotic plaques." (PMID 35990936, 2022). "Moreover, CCL2 and its receptor CCR2 are important mediators of macrophage accumulation in atherosclerotic lesions, which are considered targets to inhibit the progression of atherosclerosis." (PMID 35990936, 2022). "In addition, MCP1/CCL2 secreted by PVAT it is a factor that favors the attraction and recruitment of monocytes/macrophages towards the vascular wall, and monocyte–endothelial cell adhesion plays a key role in the initiation of atherosclerosis." (PMID 34948944, 2021). "CCL2 (or monocyte chemotactic protein-1 (MCP-1)) is a major chemoattractant for monocytes, macrophages, memory T lymphocytes, and endothelial cells and directly contributes to the pathogenesis of inflammatory diseases such as atherosclerosis, rheumatoid arthritis and diabetic nephropathy." (PMID 27820834, 2016). "CCL2 induction may contribute to impair HDL function and form atherosclerosis in CAD." (PMID 27458015, 2016). "The chemokine (C-C motif) ligand 2 (CCL2) or chemokine monocyte chemoattractant protein- (MCP-) 1 is believed to play a major role in the pathogenesis of hypertensive vascular disease and atherosclerosis and may also contribute to the pathogenesis of RA, idiopathic pulmonary fibrosis, and tumors." (PMID 25878716, 2015). "Aortas from these mice, when transplanted into apolipoprotein E (ApoE)−/− mice fed a high-fat diet, fail to express CCL2 and MIF and do not develop atherosclerosis, in contrast to the florid lesions seen in control WT aortas." (PMID 33458623, 2021). "Similar anti-inflammatory effects were observed in atherosclerosis and a cuff-induced vascular inflammation model, where Nifedipine inhibited TNF-α-induced reactive oxygen species (ROS) generation and CCL-2 gene expression, but CCL-2 protein levels were not measured in either of these studies." (PMID 36835507, 2023).
breast cancer (644 papers, 2007 to 2026). A primary or metastatic malignant neoplasm involving the breast. "Secreted into the tumor microenvironment, CCL2 promotes angiogenesis, as well as the recruitment of tumor‐associated macrophages and MDSCs in breast cancer, and plasma CCL2 levels are higher in patients with breast cancer compared with healthy individuals." (PMID 39749673, 2025). "Here, we found that CCL2/HGF-mediated glycolysis was shown to be associated with alterations in nucleotide metabolism in breast cancer cells." (PMID 40736024, 2025). "The production of CCL2 and other adipokines by breast cancer cells and cancer-associated adipocytes, such as lauric acid and leptin, invites TAMs to the TME." (PMID 40422244, 2025). "CAAs are defined as high producers of CXCL8, CCL2, and IL-6 associated with breast cancer development." (PMID 40076892, 2025). "In this study, we investigated the potential correlation between breast cancer susceptibility and eight specific SNPs within both the CCL2 and CXCL12 genes among the Chinese population." (PMID 39703847, 2024). "Recently, a Mendelian Randomization analysis that systematically screened 41 cytokines identified that CCL2 was significantly associated with an increased risk of overall breast cancer, as well as ER-positive breast cancer." (PMID 39703847, 2024). "Studies have linked CCR2 expression and CCL2 secretion to poor prognosis in various cancers, including breast cancer, pancreatic cancer, and prostate cancer." (PMID 39201480, 2024). "Elevated levels of CCL2 are often associated with the progression of diseases, such as esophageal cancer, breast cancer, colorectal cancer, prostate cancer, melanoma, gastric cancer, and ovarian cancer." (PMID 38769475, 2024). "In the stratified analyses, rs1024611 in CCL2 was found to increase the susceptibility to breast cancer in the BMI≥24 (kg/m2) subgroup (dominant model: OR=1.44, 95% CI=1.09-1.91; addictive model: OR=1.22, 95% CI=1.01-1.47)." (PMID 39703847, 2024). "The association between rs1024611 in CCL2 and breast cancer was only found in women with a BMI of ≥24kg/m2." (PMID 39703847, 2024). "CCL2 is associated with increased tumor grade and decreased relapse-free survival in breast cancer patients and promotes bone metastasis and osteolysis in mice." (PMID 37025604, 2023). "When challenged with a chemical carcinogen, CCL2 overexpressing mice had increased mammary cancer susceptibility, with decreased tumour latency and decreased tumour-free survival." (PMID 37108548, 2023). "A key role for CCL2 in early breast tumorigenesis is through increasing mammographic breast density, which is an independent risk factor for breast cancer." (PMID 37108548, 2023). "In breast cancer, a specific increase of CCL2 alone is also associated with cancer metastasis promotion; and when CCL2 was found overexpressed in breast cancer tissues, those patients had a poorer prognosis." (PMID 37181043, 2023). "Here, our findings demonstrate that chronic inflammation caused by bacteria can enhance breast cancer lung metastasis by recruiting tumor-promoting MHCIIhi neutrophils via the chemokine CCL2." (PMID 37563136, 2023). "C–C motif chemokine 2 (CCL2) induces infiltration and accumulation of TAMs in breast cancer and is positively associated with cancer progression." (PMID 37658431, 2023). "Here, we study the interplay between the matrix molecule tenascin-C (TNC) and chemokine CCL2, both elevated in and associated with the progression of breast cancer and playing key roles in myeloid immune responses." (PMID 37176074, 2023). "CCL2 has been implicated in tumour development, and its expression by tumour cells is associated with poor prognosis in women with breast cancer." (PMID 37108548, 2023). "CCL2, known as monocyte chemoattractant protein 1 (MCP-1), attracts monocytes and was shown to be associated with the spread of breast cancer in the body." (PMID 37445941, 2023).
breast cancer (continued). "IL4 signaling in macrophages also transcriptionally regulated other genes causally associated with mammary cancer lung metastasis, including Ccl2, Csf1, Ccr1, Hgf and Flt1." (PMID 36077870, 2022). "Long noncoding RNA associated with breast cancer brain metastasis (lnc-BM) is upregulated in metastatic cells where it induces the expression of CCL2 via the activation of the JAK2/STAT3 pathway." (PMID 35202089, 2022). "Based on biomedical findings, CCL2 expression in breast carcinomas was highly associated with macrophage infiltration, and its expression was correlated with poor prognosis in breast cancer patients." (PMID 36497286, 2022). "First reported in breast cancer cells, cancer-associated adipocytes are known to be involved in the activation of adipokine CCL2 and lead to the further activation of cancer stem cells." (PMID 35123536, 2022). "The high expression of CCL2 in the plasma of breast cancer patients is confirmed by enzyme-linked immunosorbent assay (ELISA), but the low concentration of CCR2." (PMID 36403055, 2022). "Many studies have investigated the role of CCL2 in breast cancer and suggest that CCL2 increases breast cancer risk and tumor progression." (PMID 34771552, 2021). "CCL2 is expressed by both stromal cells and tumor cells and is associated with poor prognosis in breast cancer." (PMID 33968034, 2021). "In human breast cancer, the level of CCL2, produced by monocytic cells and tumor cells, was associated significantly with TAM accumulation and was a significant indicator of early relapse and vessel invasion of tumor cells." (PMID 34804061, 2021). "Peroxidase enzymes, TGFB, TNFA and CCL2 have been demonstrated to influence the stromal environment through effects on fibroblast activity and immune cells, as well as contributing to breast cancer risk and development." (PMID 34771552, 2021). "We conclude that, in this study, we provided a possible mechanism that underlies TGF-β-dependent regulation of the CCL2 gene promoter in triple-negative advanced breast cancer cells." (PMID 34239022, 2021). "Human serum CCL2 has been associated with a chronic pro-inflammatory state and was suggested as a biomarker for malignant disease such as prostate and breast cancer." (PMID 33540898, 2021). "The secretomic profile that associated with cancer relapse and high grade breast cancer showed induced secretion of the proteins IL-6, CCL2 and PAI-1, all linked to cancer stem cell activation, metastasis and priming of the pre-metastatic niche." (PMID 34090457, 2021). "CCL2 is implicated in the recruitment of MDSCs in several murine cancer models, including lung carcinoma, melanoma, colorectal cancer, and breast cancer." (PMID 33123472, 2020). "Elevated expression of tumor and systemic CCL2 is associated with poor prognosis in breast cancer patients." (PMID 33247183, 2020). "A previous study showed that CCL2 induces chemokine cascade signaling and subsequently promotes breast cancer metastasis by elevating retention of metastasis-associated macrophages." (PMID 32986377, 2020). "A role of CCL2 mRNA in the basal subtype has been described in a breast cancer mouse model recently; however, tumor-associated macrophages induce CCL2 expression in tumor cells." (PMID 32429318, 2020). "High levels of CCL2 in the tumor microenvironment, as well as high circulating concentrations of this chemokine, have been associated with poor prognosis in breast carcinoma patients." (PMID 33114046, 2020). "The correct reference is “Kitamura, T.; Qian, B.Z.; Soong, D.; Cassetta, L.; Noy, R.; Sugano, G.; Kato, Y.; Li, J.; Pollard, J.W. CCL2-induced chemokine cascade promotes breast cancer metastasis by enhancing retention of metastasis-associated macrophages." (PMID 31146450, 2019).